KDR (kinase insert domain receptor)
Diseases named in the same sentence as KDR in open-access papers (continued):
Sharing a sentence is not in itself a finding about the gene and the disease.
intracranial aneurysm (2 papers, 2019 to 2022). "The complementary pairing of KDR mRNA is mir-370-3p, which regulates the activity of the AKT/FOXO1 signaling pathway involved in intracranial aneurysm." (PMID 35800988, 2022).
invasive carcinoma (2 papers, 2005 to 2017). A carcinoma that is not confined to the epithelium, and has spread to the surrounding stroma. "Comparing the expression of angiogenic markers between the groups of DCIS with (n=104) vs DCIS without (n=96) coexisting invasive carcinoma revealed that expression of VEGF-C, KDR, Flt-4, and ETAR was significantly more frequent in pure DCIS than in DCIS with an adjacent invasive carcinoma." (PMID 15841074, 2005). "With respect to our findings, it is conceivable that determination of VEGF-C, ETAR, KDR, and Flt-4 expression may facilitate discrimination of a more angiogenic subset within the group of non-high-grade DCIS without coexistent invasive carcinoma." (PMID 15841074, 2005).
ischemic disease (2 papers, 2012 to 2025). Lack of blood supply to an area of the body, resulting in impairment of tissue oxygenation. "Noteworthy, the administration of purified CD34+/KDR+ progenitor cells promoted vascular regeneration in ischemic limbs of mice and might therefore provide an interesting tool for therapeutic angiogenesis in ischemic diseases." (PMID 22506045, 2012).
ovarian hyperstimulation syndrome (2 papers, 2009 to 2014). A complication of ovulation induction in infertility treatment. "The objective of this investigation was to determine if kinase insert domain/vascular endothelial growth factor receptor 2 (KDR/VEGFR2) genetic variation was associated with the development of ovarian hyperstimulation syndrome (OHSS) in patients undergoing controlled ovarian hyperstimulation (COH)." (PMID 24886133, 2014).
peripheral vascular disease (2 papers, 2014 to 2023). Any disorder affecting blood flow through the veins or arteries outside of the heart. "Further, impaired mobilization of CD34+KDR+ EPCs in diabetic subjects was shown, as was a reduction of CD133+/KDR+ EPCs and CD34+KDR+ EPCs in T2D and its association with peripheral vascular disease risk." (PMID 35909294, 2023).
polyp (2 papers, 2014 to 2024). A usually exophytic mass attached to the underlying tissue by a broad base or a thin stalk. "Specifically, compared with normal tissues, monocytes, pDCs and epithelial subsets had increased expression levels of VEGFA and/or VEGFB, while endothelial cells had increased expression levels of VEGF receptors FLT1 and KDR in three polyp subtypes." (PMID 38264936, 2024).
prediabetes (2 papers, 2025 to 2026). "The CD14+/KDR+ expression in MOMCs incubated with HDL from T2D patients was lower than that observed in prediabetes and normoglycemic individuals (46% vs. 52% and 61%, respectively; p = 0.002)." (PMID 41893343, 2026).
prostate adenocarcinoma (2 papers, 2003 to 2021). "Mice bearing PC-3 human prostate adenocarcinoma xenografts were treated with ZD6474, a VEGF receptor-2 (KDR) tyrosine kinase inhibitor." (PMID 14612898, 2003).
pyometra (2 papers, 2015 to 2020). "In fact, the endometrial neovascularization in the pyometra group is confirmed by higher immunostaining of VEGF-A and its receptors (FLT-1 and KDR), and angiogenesis is associated with simultaneous increased uterine expression of the COX-2 inflammatory marker." (PMID 32784584, 2020).
acute pancreatitis (1 paper, 2017). An acute inflammatory process that leads to necrosis of the pancreatic parenchyma. "The comparative analysis of genotypes and statistical data obtained revealed that VEGFR-2 (KDR) 604A>G polymorphism had a strong association with pancreatic inflammatory pathology (acute pancreatitis)." (PMID 28218664, 2017).
AIDS (1 paper, 2011). A syndrome resulting from the acquired deficiency of cellular immunity caused by the human immunodeficiency virus (HIV). "Indeed, like VEGF, its cognate receptor, VEGFR2 (KDR), is also upregulated in AIDS-KS primary lesions as well as in AIDS-KS spindle cell cultures." (PMID 21559457, 2011).
anaplastic ependymoma (1 paper, 2023). Anaplastic ependymoma is a rare, malignant type of ependymoma that most often arises in the supratentorial region of the brain of children and young adults and that manifests with variable symptoms including headaches, nausea, vision impairment, memory loss and difficulty walking. "In addition, the ERBB4 variant (rs839541) was reported in anaplastic ependymoma Grade III, and the KDR variant c.798+54G>A was reported in anaplastic ependymoma Grade III, ACP, and MPE tumors." (PMID 37273678, 2023).
ataxia telangiectasia (1 paper, 2018). Ataxia-telangiectasia is the association of severe combined immunodeficiency (affecting mainly the humoral immune response) with progressive cerebellar ataxia. "WSE correlated with mutations in the genes SMARCB1 (p=0.002), Ataxia telangiectasia mutated (p=0.004), Kinase Insert Domain Receptor (p=0.006), and were borderline significant in RET and EGFR exon." (PMID 30093964, 2018).
autism spectrum disorder (1 paper, 2024). A spectrum of developmental disorders that includes autism, and Asperger syndrome. "Sequencing studies in large developmental disorder cohorts previously reported de novo pLoF variants in KDR in one proband with a neurodevelopmental disorder and in another with autism spectrum disorder, as well as a de novo missense variant in a case with autism spectrum disorder." (PMID 40225914, 2024).
coronary stenosis (1 paper, 2014). Narrowing of the coronary artery lumen diameter. "Another study also reported higher levels of CD34+/KDR+ EPCs and CD34+/CD133+ EPCs in patients with severe angiographic coronary stenosis compared with those with normal coronary arteries." (PMID 24736282, 2014).
cystic hygroma (1 paper, 2024). A benign lymphatic neoplasm usually arising from the neck and characterized by cystic dilation of the lymphatic vessels. "Although with the development of next-generation sequencing technology, genetic variants such as SOX9, KDR, and BRCA1 are involved in the pathogenesis of cystic hygroma, the specific pathogenesis of cystic hygroma remains unclear." (PMID 38650036, 2024).
diffuse intrinsic pontine glioma (1 paper, 2019). A neuroglial tumor that arises from the middle portion of the brain stem. "DNA analysis of a diffuse intrinsic pontine glioma (DIPG), TH02_0092_S01, revealed copy number gains of KDR (OMIM 191306), KIT (OMIM 164920), and PDGFRA, located on 4q12." (PMID 31651965, 2019).
dilated cardiomyopathy (1 paper, 2025). Cardiomyopathy which is characterized by dilation and contractile dysfunction of the left and right ventricles. "In this study, bioinformatics analyses and multiomics techniques were employed to elucidate the molecular mechanisms underlying dilated cardiomyopathy (DCM) and to identify five potential biomarkers: VCL, ABCB1, JAK2, KDR, and NGF." (PMID 40217309, 2025).
gallbladder tumors (1 paper, 2021). "Two distinct endothelial cells (KDR+ and ACKR1+), which were involved in angiogenesis and lymphangiogenesis, showed remarkable ligand–receptor interactions with primary GC cells and macrophages in gallbladder tumors." (PMID 34185421, 2021).
gestational trophoblastic disease (1 paper, 2017). "Even when PAK2 had being poorly studied in PE, we know that it is directly involved in gestational trophoblastic disease and that endothelial cells PAK and/or CDC42 are directly involved with KDR and consequently essential for endothelial cells organization." (PMID 28789679, 2017).
hereditary cancer syndromes (1 paper, 2017).
ischemic cardiomyopathy (1 paper, 2020). Ischemic cardiomyopathy is a cardiomyopathy in which a weakness in the muscle of the heart due to inadequate oxygen delivery to the myocardium with coronary artery disease being the most common cause. "Patients with ischemic cardiomyopathy (ICM) showed significantly lower CD34+KDR+ EPC levels when compared to non-ischemic dilated cardiomyopathy patients (DCM) (0.0010 ± 0.0007 vs 0.0030 ± 0.0024 cells/100 leukocytes, p = 0.032)." (PMID 32448383, 2020).
leishmaniasis (1 paper, 2024). Infectious disease that is transmitted through the bite of hematophagous female phlebotomine sand flies. "Our in silico approach involved predicting the affinities of MIL and NMIL to critical proteins involved in leishmaniasis, including Vascular Endothelial Growth Factor A (VEGF-A), the Kinase insert domain receptor (KDR1), and apoptotic-regulator proteins (Bcl-2-associate)." (PMID 38291076, 2024).
Menstrual disorder (1 paper, 2025). Category of disorders related to menstruation. "Alterations in KDR expression or function have been linked to various menstrual disorders." (PMID 40028534, 2025).
Moyamoya disease (1 paper, 2012). Moyamoya disease (MMD) is a rare intracranial arteriopathy involving progressive stenosis of the cerebral vasculature located at the base of the brain causing transient ischemic attacks or strokes. "Although there are limitations with sample size and long-term follow-up clinical findings, it is important to determine the relationship of VEGF or KDR polymorphisms with moyamoya disease and collateral vessel formation after surgery." (PMID 23077562, 2012). "The frequencies and distributions of four VEGF (−2578, −1154, −634, and 936) and KDR (−604, 1192, and 1719) polymorphisms were assessed from patients with moyamoya disease and compared to the control group." (PMID 23077562, 2012). "In this study, we found VEGF or KDR polymorphisms influence moyamoya disease in subgroup analyses as well as the formation of revascularization after bypass surgery." (PMID 23077562, 2012). "We conducted a case-control study to investigate whether vascular endothelial growth factor (VEGF −2578, −1154, −634, and 936) and kinase insert domain containing receptor (KDR −604, 1192, and 1719) polymorphisms are associated with moyamoya disease." (PMID 23077562, 2012). "Therefore, we studied the relationship of VEGF and KDR polymorphisms and moyamoya disease." (PMID 23077562, 2012).
penile tumors (1 paper, 2022). "We also described, for the first time, UTRs variants (KDR, CARD11, CSMD3, and TLX3), impacting the miRNAs’ binding sites in penile tumors." (PMID 35884575, 2022).
peripartum cardiomyopathy (1 paper, 2021). Peripartum cardiomyopathy (PPCM) is an idiopathic, potentially fatal form of dilated cardiomyopathy that develops during the final month of pregnancy or within five months after delivery. "In our recently published study on women who recovered from peripartum cardiomyopathy, we found significantly higher sFlt1 (VEGF‐R) levels with a clear trend toward lower circulating CD34+/KDR+ levels compared to healthy controls, suggesting an endothelial imbalance." (PMID 33955558, 2021).
pregnancy diseases (1 paper, 2022). "KDR, also known as vascular endothelial growth factor receptor 2 (VEGFR2), was demonstrated to be elevated in the placenta of pathological pregnancy diseases (early pregnancy loss, PE) in many studies." (PMID 35991164, 2022).
spontaneous abortion (1 paper, 2015). Expulsion of the product of FERTILIZATION before completing the term of GESTATION and without deliberate interference. "The risk of KDR gene polymorphisms was investigated in Iranian women with idiopathic recurrent spontaneous abortion (RSA)." (PMID 27141535, 2015).
tumor (4,126 papers, 1999 to 2026). "KDR, a key regulator of angiogenesis, is highly expressed during tumor angiogenesis and is associated with poor prognosis." (PMID 40496617, 2025). "Studies reported elevated PIVKA-II was associated with tumor progression and angiogenesis through the KDR-PLC-γ-MAPK signaling pathway." (PMID 37109105, 2023). "CD34, Prox-1, FLT4, and KDR are associated with endothelial cell signaling, vascularization, and angiogenesis during tumor formation." (PMID 37046832, 2023). "In vivo studies by da Silva and colleagues reported that endothelial α3β1 acted as a repressor of pathological angiogenesis, as its deletion enhanced tumor-associated angiogenesis through the upregulation of KDR (VEGFR2)." (PMID 35269439, 2022). "Three over-expressed, amplified, and mutated molecules were identified as tumor antigens, i.e., KDR, COL1A2, and SAMD9, and found to be associated with unfavorable prognosis." (PMID 34815785, 2021). "In a cohort study, including 17 HL-prone families, a predisposing mutation (p.A 1065T) in the KDR gene was identified and suggested to enhance tumor proliferation." (PMID 33363029, 2020). "VEGFR2 also known as KDR is an endothelium-specific receptor, that is highly expressed on tumor-associated endothelial cells." (PMID 32998422, 2020). "VEGFR2, expressed mostly in endothelial neovascular tumor cells, is generally identified in endothelialvascular cells by a gene encoding the kinase insert domain receptor (KDR)." (PMID 34803261, 2020). "For instance, the presence of KDR p.Q472H variant was previously shown to alter tumor angiogenesis and vascularization." (PMID 28137276, 2017). "A larger number of samples are needed to validate the KDR mutation and its characteristic role in tumor recurrence." (PMID 24599305, 2014). "VEGFR2, also known as FLK-1 or KDR, is an angiogenesis-associated receptor expressed on tumor endothelial cells." (PMID 21385454, 2011). "This indicates that somatic SNVs in NOTCH1, JUN, and KDR genes may cause cancer cells to develop at various speeds and result in varying localized colonization of different cell types in the tumor." (PMID 38811597, 2024). "Suppressing KDR expression has been shown to inhibit tumor-associated angiogenesis." (PMID 39770505, 2024). "Tumour aggressiveness and angiogenesis are strongly associated with KDR (Flk-1/VEGFR-2) kinase." (PMID 38904116, 2024). "Taken together, our data provide evidence that germline variants, in this case KDR Q472H, might interact with somatic tumor driver mutations to further promote tumor progression and could also support novel therapeutic modalities." (PMID 38201446, 2023). "In the tumor of the present study, another intronic variant of KDR, c.1413-20C>G, was detected." (PMID 37273678, 2023). "Thus, the decreased expression of KDR seen in our analysis associates with a stronger immune response and a subsequent delay in tumor recurrence." (PMID 36195959, 2022). "Out of five patients, 40% had somatic tumor mutations present in KDR and/or KIT in ccfDNA." (PMID 34298235, 2021). "The data showed a tendency between the heterosis genetic model of KDR rs1870377 and time to tumour progression, having the homozygous A and T increased risk to disease progression (HR = 1.4, 95% CI (1.0–2.0), p = 0.054) and to death (HR = 1.7, 95% CI (1.0–2.7), p = 0.034)." (PMID 33353148, 2020). "Specifically, VEGFR-2/kinase insert domain receptor (KDR) is part of the major signaling pathway that plays a significant role in tumor angiogenesis, which is associated with the development of various types of tumor and metastasis." (PMID 26325365, 2015).
tumor (continued). "VEGFB and KDR are often associated with angiogenesis‐mediated resistance because they stabilise the tumour microenvironment by ensuring an adequate supply of oxygen and other nutrients required for tumour growth, further adjusting the tumour microenvironment for optimum disease progression." (PMID 38426619, 2024). "It is found that coculture with tumor tissue upregulates vascular endothelial growth factor (VEGF) receptor-2 (VEGFR2/KDR) in lung capillary cells." (PMID 41275332, 2025). "Activation of KDR enhances tumor angiogenesis and growth by upregulating oncogenic factors such as Enhancer of Zeste Homolog 2 (EZH2), which is associated with increased cell proliferation and migration." (PMID 38260532, 2025). "These cells express KDR at both mRNA and protein levels, facilitating autocrine signaling that promotes tumor cell survival and proliferation." (PMID 38260532, 2025). "This study suggested that dysregulated VEGF/KDR signaling contributed to the tumor’s pathogenesis and progression through enhanced blood vessel formation." (PMID 40710426, 2025). "This inhibition was achieved by reducing the expression of VEGF and its receptor KDR/flk-1, ultimately leading to the suppression of tumor growth." (PMID 40756346, 2025). "The objective of this study was to evaluate the expression of VEGFA and KDR proteins in cRCC and their correlation with neo-angiogenesis and postoperative tumor relapse." (PMID 39000466, 2024). "As mRNA expression does not necessary corresponds to protein expression, next immunohistochemistry was applied to detect the occurrence and cellular localization of VEGFA and KDR in tumor tissues." (PMID 39000466, 2024). "For the characters of the tumor cells, we observed notably enriched angiogenic activities and an overexpression of KDR." (PMID 39409106, 2024). "As a most critical factor in regulating angiogenesis, KDR is widely involved in tumor development and invasion." (PMID 39116105, 2024). "The histopathological and molecular features of the tumor, including mutations in ABL1, CCND1, CSF1R, FGFR4, KDR, and MALAT1-GLI1 fusion, are elucidated and discussed in the context of diagnostic, prognostic, and therapeutic considerations." (PMID 38732067, 2024). "SDC1 exhibited a greater tumor mutational burden (TMB) score, while ERBB2, KDR, FGF2, KIT, FGFR1, and FGF1 showed lower TMB scores." (PMID 38189813, 2024). "According to this study, PTK6 expression was positively correlated with CD160, IL10RB, and PVRL2 while being negatively correlated with ADORA2A, BTLA, CSF1R, and KDR in the other tumor types." (PMID 38573548, 2024). "Certain proteins, such as HER2, kinase insert domain receptor (KDR), CD49d, C-X-C motif chemokine receptor 4 (CXCR4), and CD44, were found to be associated with tumor recurrence or distant organ metastasis." (PMID 38542535, 2024). "Significantly, DNA sequencing unveiled missense mutations in ABL, CCND3, CSF1R, KDR, and FGFR4, potentially contributing to tumor progression and angiogenesis in PF." (PMID 38732067, 2024). "KDR expression in endothelial meshwork was found in only 9% of cRCC, whereas 2% of the cRCC displayed positive KDR reaction in the cytoplasm of tumor cells." (PMID 39000466, 2024). "VEGFB and KDR were observed to have a significantly higher median expression when compared to samples with pN0 in tumour samples with pN3 status." (PMID 38426619, 2024). "The main tumor susceptibility genes in CBC3T-1 cells included BARD1, KDR, FAT1, HNF1A, BRCA2, FANCA, and BRCA1." (PMID 37966669, 2024).